IGKV3-11 (immunoglobulin kappa variable 3-11)
Description:
V region of the variable domain of immunoglobulin light chains that participates in the antigen recognition. Immunoglobulins, also known as antibodies, are membrane-bound or secreted glycoproteins produced by B lymphocytes. In the recognition phase of humoral immunity, the membrane-bound immunoglobulins serve as receptors which, upon binding of a specific antigen, trigger the clonal expansion and differentiation of B lymphocytes into immunoglobulins-secreting plasma cells. Secreted immunoglobulins mediate the effector phase of humoral immunity, which results in the elimination of bound antigens. The antigen binding site is formed by the variable domain of one heavy chain, together with that of its associated light chain. Thus, each immunoglobulin has two antigen binding sites with remarkable affinity for a particular antigen. The variable domains are assembled by a process called V-(D)-J rearrangement and can then be subjected to somatic hypermutations which, after exposure to antigen and selection, allow affinity maturation for a particular antigen.
Synonyms: IGKV311; L6
Tractability: Antibody: UniProt places it where antibodies can reach, with medium confidence; UniProt predicts a signal peptide or a membrane-spanning region; its Gene Ontology location is reachable by antibodies, with medium confidence; the Human Protein Atlas places it where antibodies can reach.
Gene: Immunoglobulin variable (V) gene on chromosome 2 (89,027,171 to 89,027,731, reverse strand). Ensembl gene ENSG00000241351.
Subcellular location: Secreted; Cell membrane
Subcellular location (Human Protein Atlas): Cytosol; Plasma membrane; Predicted to be secreted
Pathways (Reactome):
Immune System: Antigen activates B Cell Receptor (BCR) leading to generation of second messengers; CD22 mediated BCR regulation; Classical antibody-mediated complement activation; FCERI mediated Ca+2 mobilization; FCERI mediated MAPK activation; FCERI mediated NF-kB activation; FCGR activation; Fc epsilon receptor (FCERI) signaling; Immunoregulatory interactions between a Lymphoid and a non-Lymphoid cell; Initial triggering of complement; Regulation of Complement cascade; Regulation of actin dynamics for phagocytic cup formation; Role of LAT2/NTAL/LAB on calcium mobilization; Role of phospholipids in phagocytosis
Disease: FCGR3A-mediated IL10 synthesis; FCGR3A-mediated phagocytosis; Potential therapeutics for SARS
Hemostasis: Cell surface interactions at the vascular wall
Vesicle-mediated transport: Scavenging of heme from plasma
Gene Ontology:
Molecular function: antigen binding
Biological process: immune response
Cellular component: blood microparticle; extracellular exosome; extracellular region; immunoglobulin complex; plasma membrane
Homologues: Orthologues: mouse Igkv18-36 (70% identical), rat Igkvl13 (67% identical). Paralogues in human: IGKV3D-11 (98% identical), IGKV3OR2-268 (93% identical), IGKV3-15 (91% identical), IGKV3-20 (91% identical), IGKV3D-20 (91% identical), IGKV3D-15 (90% identical), IGKV3-7 (90% identical), IGKV3D-7 (88% identical), IGKV1D-13 (71% identical), IGKV1-9 (70% identical), IGKV1-39 (70% identical), IGKV1D-39 (70% identical), and 81 more.
Diseases named in the same sentence as IGKV3-11 in open-access papers:
IGKV3-11 is named in the same sentence as 1 disease in open-access papers, as found by Europe PMC text mining. Sharing a sentence is not in itself a finding about the gene and the disease. The quoted sentences say what the papers report.
glioma (1 paper, 2021). A benign or malignant brain and spinal cord tumor that arises from glial cells (astrocytes, oligodendrocytes, ependymal cells). "In glioma grade III, highly activated DEGs included CFAP45, PLBD1, RASSF9, IGKV3-11, IGKV1-5, and NTS, while highly downregulated DEGs included NPAS4 and LINC01007." (PMID 33948562, 2021).